ATP5PB (ATP synthase peripheral stalk-membrane subunit b)
Description:
Subunit b, of the mitochondrial membrane ATP synthase complex (F(1)F(0) ATP synthase or Complex V) that produces ATP from ADP in the presence of a proton gradient across the membrane which is generated by electron transport complexes of the respiratory chain. ATP synthase complex consist of a soluble F(1) head domain - the catalytic core - and a membrane F(1) domain - the membrane proton channel. These two domains are linked by a central stalk rotating inside the F(1) region and a stationary peripheral stalk. During catalysis, ATP synthesis in the catalytic domain of F(1) is coupled via a rotary mechanism of the central stalk subunits to proton translocation (Probable). In vivo, can only synthesize ATP although its ATP hydrolase activity can be activated artificially in vitro (By similarity). Part of the complex F(0) domain. Part of the complex F(0) domain and the peripheric stalk, which acts as a stator to hold the catalytic alpha(3)beta(3) subcomplex and subunit a/ATP6 static relative to the rotary elements (By similarity).
Synonyms: ATP5F1; PIG47
Tractability: Small molecule: a structure with a bound ligand is known. PROTAC: ubiquitination databases record sites on it.
Gene: Protein-coding gene on chromosome 1 (111,448,111 to 111,465,941, forward strand). Ensembl gene ENSG00000116459.
Subcellular location: Mitochondrion; Mitochondrion inner membrane
Subcellular location (Human Protein Atlas): Mitochondria
Pathways (Reactome):
Metabolism: Formation of ATP by chemiosmotic coupling
Organelle biogenesis and maintenance: Cristae formation
Gene Ontology:
Molecular function: protein binding; proton-transporting ATP synthase activity, rotational mechanism; proton transmembrane transporter activity
Biological process: proton motive force-driven mitochondrial ATP synthesis; substantia nigra development; proton motive force-driven ATP synthesis; proton transmembrane transport
Cellular component: membrane; mitochondrion; nucleus; proton-transporting ATP synthase complex; mitochondrial inner membrane; mitochondrial matrix
Genetic constraint (gnomAD): Loss-of-function variants: 21 observed, 35.29 expected, observed/expected ratio (o/e) 0.6, 90% interval 0.42 to 0.86. The upper end of that interval is the gene's LOEUF score, 0.86, which puts it in group 3 of 6, group 1 being the genes least tolerant of losing a copy. Missense variants: 293 observed, 326.2 expected, observed/expected ratio (o/e) 0.9, 90% interval 0.82 to 0.99. Synonymous variants: 108 observed, 117.86 expected, observed/expected ratio (o/e) 0.92, 90% interval 0.78 to 1.08.
Homologues: Orthologues: chimpanzee ATP5PB (99% identical), macaque ATP5PB (91% identical), pig ATP5PB (87% identical), guinea pig ATP5PB (84% identical), mouse Atp5pb (83% identical), rat Atp5pb (74% identical), tropical clawed frog atp5pb (60% identical), zebrafish atp5pb (57% identical), Drosophila melanogaster ATPsynB (41% identical), Caenorhabditis elegans asb-2 (24% identical), Caenorhabditis elegans asb-1 (21% identical).
Diseases named in the same sentence as ATP5PB in open-access papers:
ATP5PB is named in the same sentence as 17 diseases in open-access papers, as found by Europe PMC text mining. Sharing a sentence is not in itself a finding about the gene and the disease. The quoted sentences say what the papers report.
cardiomyopathy (1 paper, 2025). A disease of the heart muscle or myocardium proper. "Chord mapping revealed core genes (e.g., NDUFB6, RPL15, ATP5PB) involved in multiple interconnected pathways.DO analysis confirmed enrichment in cardiomyopathy, coronary artery disease, and myocardial infarction, supporting the cardiovascular specificity of the identified genes." (PMID 41200169, 2025).
myxoma (1 paper, 2024). A benign soft tissue neoplasm characterized by the presence of spindle and stellate cells, lobulated growth pattern, and myxoid stroma formation. "Macrophages in myxoma were associated with the upregulation of NFKB1, PDGFC, and IL1B, as well as the downregulation of ATP5PB, HSPB1, and IFI27." (PMID 39090109, 2024).
ATP5PB also shares sentences with these, for which no sentence is quoted: tumor (4 papers); Parkinson disease (3); Alzheimer disease (2); cancer (2); Huntington disease (2); brain diseases (1); coronary artery disease (1); hepatitis B infection (1); myocardial infarction (1); neurodegenerative disease (1); neurological diseases (1); prion disease (1); thyroid cancer (1); type-2 diabetes (1); vascular dementia (1).